IL10 (interleukin 10)
Diseases named in the same sentence as IL10 in open-access papers (continued):
Sharing a sentence is not in itself a finding about the gene and the disease.
tumor (continued). "Tumor infiltrating CD4+ T cells displayed a regulatory phenotype with high IL-10 expression and low IFN-γ production." (PMID 34262562, 2021). "Partly through Il-10 and its receptor Il-10R on tumor cells, M1-like macrophages functionally acquire a pro-cancerous capability." (PMID 34711804, 2021). "In fact, IL-10 and IL-12 balance immune system response against tumor and autoimmune conditions by antagonizing each other." (PMID 34335844, 2021). "IL-10 production also correlates with the reduction of IL-12, which is a cytokine secreted by dendritic cells mainly involved in stimulating anti-tumor immunity." (PMID 34065010, 2021). "Although I didn’t isolate Tr1 cells in this investigation, several previous studies also point out the importance of IL-10-secreting Tr1 CD4 T cells for tumor immunity." (PMID 33912464, 2021). "This way, in response to inflammation, including the one produced by tumours’ brain stromal cells, high levels of immunosuppressive cytokines, such as TGFβ or IL-10, are secreted." (PMID 34831165, 2021). "Glucose-response genes such as Il-10 are subsequently activated in tumor-educated M1-like macrophages." (PMID 34711804, 2021). "IL-10 plays a role in inducing suppression of anti-tumor immunity in CLL, contributing to the state of cancer-induced T cell dysfunction." (PMID 33466674, 2021). "The transition of proinflammatory M1 macrophages to M2 TAMs with anti-inflammatory but pro-oncogenic properties is mediated by different cytokines (IL-4, IL-13, and IL-10) and molecular signals (glucocorticoids, vitamin D3) produced by tumor or stromal cells." (PMID 35008212, 2021). "In particular, IL-32β expression in metastatic mice increases the level of IL-10, an immunosuppressive cytokine, and induces infiltration of cytotoxic T cells and NK cells in tumors, resulting in the suppression of tumor growth." (PMID 34682815, 2021). "IL-10 has been shown to have anti-tumor effects, which are enhanced when combined with IL-2; these effects can potentially be harnessed for immunotherapy." (PMID 34307161, 2021). "The cytokine IL-10 is elevated in malignant clones and is known to impair cellular anti-tumor response by virtue of its ability to inhibit the production of Th1 cytokine." (PMID 34204115, 2021). "During tumor progression, M1-polarized macrophages infiltrating the tumor demonstrate a phenotype with high IL-12 and low IL-10 expressions and promote immune responses, facilitating cancer cell disruption." (PMID 34207035, 2021). "Tissue damage occurring during tumor development and the release of alarm cytokines such as IL-1α, IL-1β, and TNFα induce the production of IL-6, IL-10, IL-11, and IL-23 by tissues and myeloid cells." (PMID 33498483, 2021). "Further, constitutive activation of STATs, resulting from either prolonged IFN signaling, other extracellular stimulus (e.g., IL-10 and IL-6), and tumor cell-intrinsic alterations, has been largely correlated with radioresistance." (PMID 34830176, 2021). "The immunosuppressive role of TAB resembles that of Breg, since they promote tumor inflammation, inhibit anti-tumor T cell-dependent therapy responses and produce IL-10 and TGF-β in mouse cancer models." (PMID 33920505, 2021). "Next, we review how DLBCL cells at more advanced stages can mimic some features of Breg cells, including high PD-L1 expression and IL-10 secretion, and promote an immunosuppressive microenvironment that reinforce anti-tumour immune evasion." (PMID 34572910, 2021). "It is worth noting that IL-10 alone resulted in complete tumor regression in 3 out of 10 AJ mice, and these three mice remained healthy even after the complete 4-month follow-up period." (PMID 33912464, 2021). "Conversely, in models of breast, ovarian cancer and glioblastoma, canonical NF-κB activation in macrophages has an anti-inflammatory effect, preventing antitumor immunity and allowing tumor escape, in particular through the secretion of interleukin (IL)-10." (PMID 33572260, 2021).
tumor (continued). "Epithelial ovarian cancer-derived EVs can induce macrophages to secrete anti-inflammatory cytokine IL-10, leading to enhanced tumor growth and metastasis." (PMID 35059436, 2021). "When melanoma cells are treated with IL-10 for 48-72 hours can completely inhibit homologous CTL-mediated HLA-A2.1 limited tumor cell up to 100% specific lysis." (PMID 33391402, 2021). "E. coli NC101-mono-associated, AOM-treated Il10−/− mice presented higher tumor multiplicity than Enterococcus faecalis mono-associated, AOM-treated Il10−/− mice." (PMID 33578830, 2021). "Serum IL-10 is positively correlated with tumor stage and negatively correlated with prognosis in CRC patients." (PMID 34489941, 2021). "In a cancerous tumor, cytokines, such as IL10, secreted by the cancer cells, and the transcription factor STAT-3, cause induction of the competing enzyme arginase-1 (Arg1) in the tumor-associated microglia and macrophages (TAM)." (PMID 34575998, 2021). "IL-10 is secreted by tumor cells and is known to promote immunomodulatory responses favorable to tumor formation and growth." (PMID 34823601, 2021). "The cooperation of VEGF-A with IL-10 and prostaglandin E2 is also able to induce FasL expression on tumor endothelial cells." (PMID 33854498, 2021). "This suggests that IL-10 treatment has a very potent anti-tumor effect compared to currently used cancer therapeutic agents." (PMID 33912464, 2021). "TAMs induce IL-10 to promote tumor growth, and secrete VEGF to promote tumor angiogenesis, via the STAT3 pathway." (PMID 34445193, 2021). "There, they differentiate into tumor-promoting, immune-suppressing M2-like macrophages, secreting a variety of tumor-promoting factors such as IL-10 and VEGF, as well as additional IL-8 and GRO chemokines in a feed-forward loop." (PMID 34067257, 2021). "This cell contact-dependent cross-talk between MDSCs and macrophages, supported by IL-1β induced inflammation, enhances the pro-tumor activity of the latter group and increases the production of IL-10 by MDSCs through a TLR4-mediated mechanism." (PMID 33803806, 2021). "IL-10 expression was consistently increased in both tumor regions and cell types, whereas IL-10R was differentially expressed, with higher levels in IC compared to TC." (PMID 33672843, 2021). "Other CSC-secreted factors include IL-10 and TGF-β, which also suppress tumor-associated microglia/macrophage function and generate a more immunosuppressive (M2) phenotype." (PMID 34203727, 2021). "M2c phenotype releases IL-10 into the microenvironment creating a scenario for tumor evasion and enhancing tumor metastasis." (PMID 34177892, 2021). "Inhibiting HO-1 would increase tumor-killing and reduce IL-10 production directly or indirectly by reducing TAMs." (PMID 34066839, 2021). "The development of an experimental system that contains these immune cells, as well as tumor cells, to better reflect the true complexity of the tumor microenvironment will be key to further delineating the mechanism of IL-10 in regulating ICI immunotherapy." (PMID 34769278, 2021). "Tregs—Tregs are a subset of CD4 T-cells that sustain an immunosuppressive tumor microenvironment via secretion of IL10 and TGFβ." (PMID 34944848, 2021). "The production of IL-10 by accumulating M2-like macrophages contributed to developing an immunosuppressive microenvironment favoring tumor growth." (PMID 34606408, 2021). "FASN inhibition significantly suppresses the expressions of TNF-α, IL-6, IL-10, and ROS in TAMs, thereby impairing their pro-tumor activity." (PMID 34742349, 2021). "Inhibitory effects of NK cells were detected in OSCC in peripheral blood and tumor tissue, with increased expression of suppressive cytokines interleukine-10 (IL-10) and tumor growth factor-β (TGF-β) and decreased expression of activating receptor NKp46." (PMID 34066837, 2021).
tumor (continued). "Despite strong evidence suggesting that IL-10 plays an important role in promoting immune tolerance, numerous studies have also highlighted the anti-tumour potential of IL-10." (PMID 33401460, 2021). "DAMPs or TAAs released by dying tumor cells caused by radiation include not only immune enhancing elements such as calreticulin and HMGB1 but also immunosuppressive factors such as IL-10 and TGF-β." (PMID 33968889, 2021). "In the tumor microenvironment, TAMs contribute to the anti-inflammatory status because of their high expression of interleukin-10 (IL-10) and mannose receptor (MR, CD206), and low expression of IL-12." (PMID 34204889, 2021). "Immunosuppressive factors, such as IL-10 and tumor growth factor β (TGF-β), can be secreted by tumor cells, Tregs, and tumor-associated macrophages (TAM)." (PMID 33728333, 2021). "In preclinical studies, PD-1/PD-L1 blockade increased IL-10 secretion by tumor infiltrating dendritic cells (DCs) and upregulated PD-L1 on DCs, leading to tumor immune escape." (PMID 33467713, 2021). "On the contrary, during the advanced stages of tumor progression, TAMs are of M2-like phenotype, characterized by low IL-12 and high IL-10 expressions resulting in a low tumoricidal activity." (PMID 34207035, 2021). "The inhibition of IL-10 strengthened the effect of anti-PD-1 antibodies in expanding tumor-specific CD8+ T cells, and thus reinforced their antitumor action." (PMID 33467713, 2021). "The combination of chemo- and keto-dietary treatment resulted in a decrease of TNFα, an increase of IL-10, lower serum insulin in comparison to the control group, and a significant decrease in tumor burden." (PMID 34885122, 2021). "Conversely, the activation of any M2 sub phenotypes culminates in the liberation of cytokines, such as IL-10, that enhance tumor growth." (PMID 34177892, 2021). "Mediators released by tumor-infiltrating lymphocytes, such as T helper 2 (Th2)-cell-derived IL-4 and regulatory T (Treg) cell, and tumor-cell-derived IL-10, VEGF-A, TGF-β, and PGE2 activate an immunosuppressive program in TAMs." (PMID 34638388, 2021). "IL-10 is an immunosuppressive cytokine that can mediate immune tolerance and tumor immune escape and also plays a key role in anti-inflammation." (PMID 34095321, 2021). "Since cytokines are responsible for the induction of immune cells against tumors, we evaluated the levels of IL-10 in tumor sections of experimental and control animals." (PMID 34066839, 2021). "MDSC, especially Gr-1+CD11b+CD115+ (monocytic) MDSC, can also generate tumor specific Tregs in tumor-bearing mice and in cancer patients by secreting IL-10 and TGF-β or by arginase activity." (PMID 33854498, 2021). "Tumor-derived factors within the TME induce cyclooxygenase-2 (COX-2) activity in MDSCs, which has been implicated in promoting IDO1, IL-10, ARG1, iNOS, and PGE2." (PMID 34065010, 2021). "IL10 has been detected in the tumor microenvironment of many cancer types and has been thought to promote tumor immune escape by polarizing TAMs to the M2 phenotype and inhibiting the functions of antigen presenting cells." (PMID 34583750, 2021). "Blocking IL-10 activity also enhances cytotoxic T cell function in the peritoneal cavity and restricts tumor spread." (PMID 34503128, 2021). "It was also associated with a reduction in the development of regulatory T-cells that produce IL-10 and increased numbers of MDSCs in the tumor microenvironment." (PMID 34771569, 2021). "The tumor and organ indexes, including liver and spleen, and IL-2 and IL-10 serum levels also notably decreased, and the amounts of WBC, HGB, and PLT dramatically increased." (PMID 34475822, 2021). "Th17 cells expressing IFNγ can be tumor-cytolytic, while those expressing immune suppressive cytokine IL-10, promote tumor growth." (PMID 34943886, 2021).
tumor (continued). "Combination BRAF-MEKi can shape the tumor microenvironment by reducing immunosuppressive factors such as vascular endothelial growth factor, IL-6, IL-10, and TGF-β which corresponds with increasing tumor infiltrating lymphocytes." (PMID 34944961, 2021). "In lung adenocarcinoma, IL-10 promotes tumor aggressiveness via the upregulation of CIP2A transcription." (PMID 33003428, 2020). "Whilst there is little information on its anti-tumour immunomodulatory effects, studies have shown that C3G reduced rheumatoid arthritis presentation, and concurrently increased IL-10, Tregs, and decreased IL-6, IFN-γ and NK cell activity." (PMID 32183059, 2020). "Their results detected a high level of IL-10 in the saliva and tumor environment, distinguishing the OSCC patients from the controls." (PMID 32899735, 2020). "Wnt5a induced M2 polarization of TAMs by regulating CaKMII-ERK1/2-STAT3 pathway-mediated IL-10 secretion, thereby enhancing tumor growth, invasion and metastasis of CRC." (PMID 32228612, 2020). "As another surrogate marker for the presence of tumor cells, we measured the levels of circulating human IL-6 and IL-10 in the NSG mice bearing BC-1-Fluc cells on day 19 after tumor inoculation." (PMID 32235878, 2020). "We recently identified that intratumoral PD-1+Lag3+Tox+ exhausted tumor antigen-specific T cells not only lose functionality (e.g., IFNγ, TNFα), they progressively express IL-10 specifically in the TME." (PMID 33584701, 2020). "In support of IL-10 tumor suppressor action, several studies observed that IL-10 was able to induce AML blasts apoptosis in vitro probably through the inhibition of proinflammatory cytokines production, such as IL-1α, IL-1β, IL-6, GM-CSF and TNF-α." (PMID 32443460, 2020). "As chronic intestinal inflammation can lead to tumor formation, the relationship between the degree of intestinal inflammation and large bowel tumorigenesis was analyzed for IL‐10−/− and DKO mice." (PMID 32350866, 2020). "In contrast, cetuximab induced production of anti-inflammatory and tumor-promoting mediators, including IL-10 and VEGF activating M2-macrophages in co-culture of CRC cell line and human monocyte-derived macrophages." (PMID 33194645, 2020). "The increased IL-10 level and reduced IL-12 level consequently skew the immunity toward a tumor-promoting type 2 response." (PMID 32793192, 2020). "We tested the effect of inflammatory cytokines commonly found in tumor microenvironment including IL-1β, IL-6, IL-10, TNF-α, and IFN-γ on TDO2 expression on MUM cells." (PMID 32050636, 2020). "Evidence from multiple human malignancies showed IL-10 participated in tumor immunity and exhibited therapeutic potential." (PMID 32348468, 2020). "This is consistent with the finding that depletion of MDSCs results in a remarkable reduction in IL-10 levels, and concomitantly, better outcomes leading to inhibition of tumour progression." (PMID 32931721, 2020). "At present there is a lack of substantial information relating to the role of immunosuppressive IL-10-producing B cells in affecting tumor progression in humans." (PMID 33569063, 2020). "IL-10 was also likely responsible for suppressing the Notch1 expression in DN2a T cells, since notch 1 expression in DN2 T cells and transition from DN2 to DN3 was normalized in tumor-bearing IL-10−/− mice." (PMID 32582141, 2020). "It develops in response to tumor-derived factors and releases IL10, IL12, TNFα, TNFβ, VEGF, CCL20, CCL22, and MMP9, thereby supporting tumor growth and metastases and acting as an immunosuppressant." (PMID 32900001, 2020). "Another study in melanomas also suggested that autophagosomes released by tumor cells convert macrophages into an immunosuppressive M2-like phenotype that is characterized by PD-L1 and IL-10 expression." (PMID 32944395, 2020). "BRAF inhibitor-resistant tumor cells also show reduced expression of target antigens, and increased production of IL-10." (PMID 33003483, 2020).
tumor (continued). "Traditional subsets of dendritic cells (DC) (cDC1 and cDC2) have been reported to be inhibited due to local factors (including IL-10), which prevented mature DCs from inducing anti-tumor immune responses in HCC." (PMID 33102213, 2020). "(ii) Tumor-induced IL-10 interferes with the interaction between thymic stromal cells and IL-10Rhigh DN2 T cells to arrest their development." (PMID 32582141, 2020). "The induction of PD-1+ Treg cells further raised the possibility of more IL-10 and IL-35 accumulation in tumor microenvironment, which orchestrated a positive feedback loop contributing to AML cell proliferation." (PMID 32849603, 2020). "Conversely, macrophages expressing low levels of MHCII and high levels of CD206 have been shown to be primarily tumor-supportive in nature with high production of IL-10 and poor antigen-presenting capabilities." (PMID 32354335, 2020). "In this experimental model, the role of IFN-γ would be related to tumor growth and progression, while IL-10 would participate in the antitumor immune response." (PMID 33312693, 2020). "Another potent immunosuppressive signal in the tumor microenvironment is IL-10, which can be produced by tumor cells, macrophages, regulatory T cells, as well as other components of the stroma." (PMID 32508825, 2020). "In contrast, group 1 patients with lower disease burden and slower tumor growth kinetics had less suppressive Th2 driven cytokine responses and specifically IL‐10, and expanded CD4+ effector T cells in response to treatment." (PMID 32578964, 2020). "It was reported that glutamine-synthetase (GS) controlled mTOR signaling and activated IL10-stimulated M2 macrophages with pro-tumor properties." (PMID 32486098, 2020). "Treg cells from 12B1 tumor-bearing animals suppressed the function of DCs in a TGF-β- and IL-10-dependent manner and were associated with the activation of STAT3." (PMID 32872659, 2020). "Tumor‐associated factors, such as VEGF, TGF‐β, IL‐10, PGE2, and IDO, can profoundly affect the nature of DCs by inhibition of their activation." (PMID 32976623, 2020). "At later stages when the tumor is already established their ability to express PD-L1 and secrete immunosuppressive cytokines like IL-10 further contribute to promote tumor progression due to inhibition of effector lymphocytes like CD8+ T cells." (PMID 32292409, 2020). "Tumor cells produce inhibitory cytokines such as IL-8, IL-10, and VEGF and create an unfavorable environment for DCs’ maturation." (PMID 33036192, 2020). "EV-miR-214 from tumor cells triggers IL-10 secretion and expansion of Tregs, immunosuppressive T cells, by targeting PTEN, thereby facilitating immunosuppression and tumor growth in vivo." (PMID 32503543, 2020). "What is more, the applied compounds induced immunosuppression in young mice, which was shown mainly by an increase in the percentage of Treg cells in the spleen, as well as IL-10 and in the tumor tissue, especially in the initial stages of tumor development." (PMID 32257539, 2020). "Such cytokines IL-8, IL-6, IL-1β, TNF-α, IL-10, and others can be up-regulated and consequently contribute to tumor progression." (PMID 32277014, 2020). "For each patient group, the tumor tissue exhibited a higher expression of IL-10 than adjacent paratumor tissue." (PMID 32348468, 2020). "Interleukins such as IL-2 and IL-10 were correlated to tumor aggressiveness and to serum Tg level, which suggests the involvement of interleukins would improve the efficiency of Tg evaluation system." (PMID 32655554, 2020). "The M2 type, on the other hand, is reactivated by type II cytokines (interleukin (IL)-4, -10, -13) and promotes tumor growth and invasion by producing immunosuppressive (IL-10, transforming growth factor (TGF) β) and tumor survival factors." (PMID 33066460, 2020). "We found that that IL6 was substantially expressed compared to IL10 in H. pylori-infected tumor tissues." (PMID 33569347, 2020).